PIK3CA (phosphatidylinositol-4,5-bisphosphate 3-kinase catalytic subunit alpha)
Diseases named in the same sentence as PIK3CA in open-access papers (continued):
Sharing a sentence is not in itself a finding about the gene and the disease.
breast cancer (continued). "In human neoplasms, PIK3CA is the frequently mutated gene that encodes the p110α catalytic subunit of the PI3K pathway, and was found amplified in head and neck, cervical, gastric, lung and breast cancers." (PMID 33375317, 2020). "The PI3K-AKT signaling pathway is activated in over 60% of ER+ breast cancer and contributes to resistance to ER inhibition and progression and MCF7 cells carry mutations typically found in human luminal breast cancers, including PIK3CA E545K." (PMID 31963297, 2020). "The contribution of PIK3CA gene amplifications in breast cancer tumorigenesis is not well studied, and gene amplifications are relatively infrequent in breast cancers compared to somatic mutations." (PMID 30867034, 2019). "We hypothesize that pre-existing PIK3CA mutant cells can drive tumor initiation and early progression but are lost or outgrown by other cancer driving clones in most advanced breast cancers." (PMID 30813596, 2019). "Likewise, PIK3CA (H1047R)-driven mouse mammary tumors often recur in the presence of c-myc amplification, and this combination is observed in a substantial fraction of human breast tumors." (PMID 31652979, 2019). "Although KRAS mutations are not frequent in breast cancer, they are significantly associated with PIK3CA mutations." (PMID 31652979, 2019). "Experimental studies have demonstrated that breast cancers with PIK3CA mutations are more sensitive to everolimus, but this has not been confirmed in clinical studies." (PMID 31088410, 2019). "For example, next generation sequencing analysis of a liquid biopsy from a patient with advanced breast cancer, who failed to respond to conventional chemotherapy, showed mutations in PIK3CA, PTEN and mTOR." (PMID 35582282, 2019). "Different trials testing the PIK3CA inhibitors in post-menopausal metastatic luminal breast cancer." (PMID 31069063, 2019). "In another study of HER2-amplified with or without PIK3CA mutation breast cancer cells, dactolisib induced cell death and apoptosis by activating caspase-2 and PARP cleavage." (PMID 31817676, 2019). "Findings from an in situ single-cell analysis suggest that, while mutated PIK3CA and HER2 gene amplifications occurs individually in HER2-positive breast cancer, following chemotherapy, the cell population containing both alterations was enriched in patients with resistant disease." (PMID 31146717, 2019). "In addition, it has been shown that PIK3CA mutations are associated with an elevated uptake of glucose and glutamine in colorectal cancer, and a similar effect is observed in PIK3CA mutant breast cancer cells." (PMID 30970654, 2019). "Furthermore, transgenic mouse models were used to demonstrate that expression of mutant PIK3CA induces mammary epithelial cell transformation and mouse mammary tumors." (PMID 30813596, 2019). "Strengthening the link between PIK3CA mutations and RNMT inhibition, breast cancer cell lines and mammary epithelial cells, which were insensitive to RNMT siRNA transfection, could be rendered sensitive by the expression of PIK3CA oncogenic mutants." (PMID 30991934, 2019). "Recently, the randomized, phase 3 SOLAR-1 trial showed that the treatment with alpelisib, a PI3Kα-specific inhibitor, in combination with fulvestrant prolonged progression-free survival among patients with PIK3CA-mutated, ER-positive/HER2-negative advanced breast cancer." (PMID 31391067, 2019).
breast cancer (continued). "This study provides a totally new and scientific way to holistically decipher that the pharmacological mechanisms of Damnacanthus indicus C.F.Gaertn in the treatment of breast cancer might be associated with MAP2K1, PIK3CA, and Raf1 genes." (PMID 30906409, 2019). "After MYC amplification, the next most common alterations in our analysis of the human BRCA1-deficient TNBCs were mutations and/or amplifications of PIK3CA (23/80 cases), indicating that activation of PI3K signaling is an important driver in this breast cancer subtype." (PMID 30674894, 2019). "In the present analysis of data from the ExteNET study, we evaluated PIK3CA amplifications and somatic mutations to obtain a comprehensive assessment of the prognostic and predictive significance of PIK3CA alterations in patients with early-stage HER2-positive breast cancer." (PMID 30867034, 2019). "Further, PIK3CA mutations were more frequent in tumors with PTEN mutations (46%) compared with those without PTEN mutations (24%) and this concomitant mutations (1.3%) have also been reported from Chinese breast cancers." (PMID 31289610, 2019). "A recent consensus group has suggested that for selecting breast cancer patients for clinical trials investigating new drugs, an optimal gene panel should detect AKT1, PIK3CA, PTEN, ESR1 mutations and FGFR1 amplification, in addition to the study of ER, PR, HER2 and BRCA1/2." (PMID 29273958, 2018). "When PIK3CA is mutated, the association of alpelisib, another alpha-specific PI3K inhibitor and fulvestrant showed good results in a phase I study of patients with advanced ER positive breast cancer on standard therapy." (PMID 29455659, 2018). "The documented effects of PIK3CA pathway inhibitors in advanced breast cancer, if appropriately targeted, may be translated into significant improvements in survival in early breast cancer." (PMID 30420699, 2018). "Interestingly, preclinical studies have suggested that oncogenic PIK3CA driven the development of breast cancer, and the PI3Kα-selective inhibitors shown more effective and more tolerable toxicity profile in clinical trails." (PMID 29942710, 2018). "Of the 11 nonresponder patients with breast cancer, seven received everolimus on the basis of a PIK3CA mutation (3× His1047Arg, 2× Glu545Lys, and 2× Glu542Lys) and four received everolimus on the basis of PTEN inactivation." (PMID 32914004, 2018). "Specifically, in an orthoptopic model of advanced endocrine therapy resistant, PIK3CA mutant breast cancer, we observed that combined, low-dose treatment with the mTORC1/2 inhibitor MLN-0128 and the SMAC mimetic BV6 blocked tumor growth and extended survival without evidence of substantial toxicity." (PMID 29700304, 2018). "Further, the sensitivity to pictilisib was independent of PIK3CA mutations and the combination treatment showed a remarkable anti-proliferation effect in luminal B primary breast cancer (Ki 67 staining; 37%)." (PMID 29942710, 2018).
breast cancer (continued). "MiR-152-3p might also act as a tumor suppressor in human breast cancer cells via negatively regulating PIK3CA expression to inhibit the activation of AKT and RPS6, leading to the suppression of HCC1806 cells proliferation." (PMID 29323178, 2018). "Recent studies have indicated an association between high INPP4B expression and SGK3 phosphorylation levels in PIK3CA-mutant breast cancers and melanoma, in which INPP4B-mediated activation of SGK3 enhances cell proliferation and promotes anchorage-independent cell growth." (PMID 29343273, 2018). "Although mutations in PIK3CA are common in breast cancer, they have not been reliably predictive of clinical response to drugs targeting the PI3K/mTOR pathway." (PMID 29177603, 2018). "Unfortunately, impactful PIK3CA mutations did not seem to be related to the clinical outcome of breast cancer patients; and they do not have prognostic significance in the subsequent stratification of molecular subtypes." (PMID 29636477, 2018). "It demonstrated superior inhibitory effect in cells with PIK3CA activating mutations over wild-type in breast cancer and non-small cell lung cancer xenografts." (PMID 31093356, 2018). "Moreover, two recent studies showed that mutant PIK3CA in breast cancer induces multipotency in lineage-committed basal and luminal cells, which drives plasticity and intratumor heterogeneity." (PMID 29764517, 2018). "The frequencies of prognostically favorable PIK3CA and CDH1 mutations were lower in women of African ancestry than in Whites, which may reflect differences in breast cancer risk factors across populations." (PMID 30327465, 2018). "For example, patients with advanced hormone receptor-positive PIK3CA mutant breast cancer with inadequate ctDNA suppression on palbociclib and fulvestrant could benefit from early introduction of a PI3-kinase inhibitor." (PMID 29497091, 2018). "When associated with other inhibitors such as fulvestrant, taselisib has demonstrated a higher antitumoral response in HER-2 negative and ER positive breast cancers with PIK3CA mutations if compared with the wild type." (PMID 29455659, 2018). "In contrast to the ESR1 mutations, the PIK3CA mutations were not significantly more prevalent in ER + /HER2-disease compared to other breast cancer subtypes and 14% of the PIK3CA mutant samples had more than one PIK3CA mutation." (PMID 30083595, 2018). "Recently, it was described that PIK3CA‐H1047R induces multipotency and multilineage mammary tumors." (PMID 28296140, 2017). "Out of a total of 95 breast cancer samples, 5 breast-cancer samples did not have mTOR-pathway activation, and all 5 (100%) of these had PIK3CA and PTEN mutations compared to 51/90 (57%) in the breast-cancer samples with mTOR-pathway activation (χ2p=0.0134)." (PMID 29137436, 2017). "To examine the role of PIK3CA‐H1047R and ‐E545K mutations during mammary development and their ability to induce mammary tumors, we generated transgenic mice with expression of the PIK3CA‐mutant genes under the control of the mammary epithelial‐specific MMTV promoter." (PMID 28296140, 2017).
breast cancer (continued). "However, while long‐term stabilization and partial tumor responses are observed in PIK3CA‐positive breast cancers treated with PI3Ki (NCT01219699), the majority of mutant cancers do not experience substantial regression." (PMID 28296140, 2017). "It is PIK3CA amplification rather than PIK3CA mutation status that is associated with basal-like breast cancer." (PMID 28387221, 2017). "However, when considered as a separate category, all 18 samples with mutations in both PIK3CA and PTEN genes (breast cancer, endometrial carcinoma, ovarian cancer and urinary bladder cancer) also displayed mTOR-pathway activation (χ2p=0.0471)." (PMID 29137436, 2017). "An analysis using TCGA breast cancer datasets showed that PIK3CA expression was indeed associated with copy number but not mutation." (PMID 28387221, 2017). "Interestingly, module 5 (with Mucins) is mutually exclusive with many known breast cancer drivers including PIK3CA, MAP3K1, and RUNX1." (PMID 29023534, 2017). "In addition, oncogenic activation of PIK3CA leads to intrinsic resistance of HER2-positive breast cancer cells to HER2 inhibition, and is more frequently activated in patients that exhibit acquired resistance to HER2 inhibition." (PMID 28561737, 2017). "To investigate the efficacy of the PI3K inhibitor and its association with different mutations in the PI3K pathway, we combined tamoxifen (0–16 μM) with alpelisib (0–10 μM) at a constant ratio to assess the effect on breast cancer cell lines harboring different PIK3CA pathway alterations." (PMID 28852212, 2017). "Thus, to investigate the mechanisms of resistance to BYL719, we selected the BYL719-sensitive luminal human breast cancer cell lines T47D and MCF7 harboring the H1047R and E545K PIK3CA hotspot mutations, respectively." (PMID 27048245, 2016). "In contrast, analysis of divergent breast cancer cell lines revealed that mutations in PIK3CA but not PTEN loss coincide with increased sensitivity to mTOR inhibitors." (PMID 26814435, 2016). "HCT116 cells harbor the H1047R PIK3CA-activating mutation, and the addition of BYL719 decreased AKT phosphorylation but did not decrease mTORC1 signaling, mimicking the phenotype observed in BYL719-resistant breast cancer cell lines." (PMID 27451907, 2016). "Moreover, expression of mutant PIK3CA in the mouse mammary gland induces heterogeneous mammary tumors with features resembling human breast cancer." (PMID 27048245, 2016). "Therefore, understanding the role of mutant PIK3CA in basal breast cancer (BC) subtype pathogenesis is of obvious significance." (PMID 27941987, 2016). "Moreover, in the breast cancer cell line MDA-MB-231 modified to express either PIK3CA-E545K or H1047R, both displayed increased motility, with cells expressing PIK3CA-E545K showing increased directional migration." (PMID 27489350, 2016). "However, any predominance in HR-positive breast cancer as described for PIK3CA cannot be excluded because of the low number of cases in our HR-negative cohort." (PMID 27515171, 2016).
breast cancer (continued). "In contrast, whereas a 70 % decrease in S6 phosphorylation at Ser235/236 was observed in parental cell lines, a smaller 20 % decrease occurred in resistant cells suggesting that sustained mTOR activity leads to BYL719 resistance in PIK3CA mutant breast cancer cells." (PMID 27048245, 2016). "More recently PIK3CA mutations have been shown to induce tumor heterogeneity and are associated with activation of EGFR-signaling and reduced relapse free survival in basal subtype of breast cancer." (PMID 27941987, 2016). "Consistent with a role for PDK1 in tumorigenesis, PDK1 overexpression and increased copy number in breast cancer has been shown to correlate with upstream lesions such as PTEN loss, PIK3CA mutation and EGFR amplification, and resulted in increased tumour growth, cell motility and poor prognosis." (PMID 27199173, 2016). "We then explored whether SGK1 and pNDRG1 expression correlate with clinical outcome to PI3Kα inhibition by analyzing PIK3CA-mutant breast cancer samples from 18 patients treated with BYL719 in combination with an aromatase inhibitor (NCT01870505)." (PMID 27451907, 2016). "Furthermore, we provide proof-of-principle data screening the 200 most frequently mutated genes in breast cancer in BT474 spheroids, confirmed their dependency on amplification of HER2 and oncogenic mutation of PIK3CA." (PMID 28060271, 2016). "On the other hand, recent work has also shown that activating mutations in PIK3CA, a frequent alteration in breast cancer, does not predict the response to endocrine treatment." (PMID 25886003, 2015). "Sensitivity did not seem to be related to PIK3CA mutational status or ER status, in agreement with a previous study reporting a lack of correlation of everolimus sensitivity to PIK3CA mutation in breast cancer." (PMID 26148118, 2015). "Screening TNBC/basal-like breast cancer for EGFR mutations may prove useful for directing therapy but, as in non-small cell lung cancer, accompanying mutations in PIK3CA may confer gefitinib resistance." (PMID 25969993, 2015). "Similarly, both PIK3CA mutation and PTEN loss correlated with MK-2206 sensitivity in breast cancer cell lines." (PMID 26469692, 2015). "Even though PIK3CA mutations have a high mutation frequency in breast cancer patients, it does not seem to be a good independent predictor in the context of endocrine therapy." (PMID 26473850, 2015). "In breast cancer these include, overexpression/amplification of HER2 (ErbB2/neu), activating mutations in PIK3CA, the gene encoding the α catalytic subunit of PI3K, mutation or amplification of AKT and loss of the lipid phosphatase, phosphatase and tensin homolog (PTEN)." (PMID 26095475, 2015). "The present study showed that the different types of PIK3CA mutations do not seem to have any prognostic role in breast cancer patients treated with adjuvant chemotherapy." (PMID 26452060, 2015). "While PIK3CA mutations have been shown to be associated with improved patient prognoses, these genetic aberrations have also been shown to impart resistance to trastuzumab, a common treatment option for HER2-overexpressing breast cancers." (PMID 25757876, 2015).